GRK2 (G protein-coupled receptor kinase 2)
Diseases named in the same sentence as GRK2 in open-access papers (continued):
Sharing a sentence is not in itself a finding about the gene and the disease.
breast cancer (13 papers, 2017 to 2024). A primary or metastatic malignant neoplasm involving the breast. "A previous report showed, using mouse skin tissues, glutamine attenuates itch via a rapid induction of GRK269, which is in contrast to our observation that glutamine deprivation leads to GRK2 induction and activation in breast cancer cell lines." (PMID 35641493, 2022). "β-AR signaling in breast cancer facilitates G protein-coupled receptor kinase 2 (GRK2) phosphorylation and then increases human antigen R (HuR) nuclear export by inducing phosphorylation of HuR." (PMID 33419318, 2020). "Our data put forward that in this luminal A breast cancer model GRK2 would foster HuR/HIF-1α pathways even in normoxic conditions." (PMID 32413989, 2020). "GRK2 exerts a key role in the development and progression of breast cancer growth and metastatization through its catalytic activity." (PMID 33256128, 2020). "Expression of the ELAVL1 (HuR) and ADRBK1 (GRK2) genes showed a direct correlation in breast cancer patients inspected with the web tool CANCERTOOL." (PMID 32413989, 2020). "Our previous results pointed to GRK2 as a common regulatory and transducing effector of diverse pathways that are altered in luminal and basal breast cancer." (PMID 32413989, 2020). "We have recently shown that GRK2 expression is up-regulated in different breast cancer contexts, playing a driving role in the acquisition of oncogenic features." (PMID 32413989, 2020). "Consistent with this notion, recent data have emphasized a relevant role for the GRK2/HDAC6 axis in breast cancer." (PMID 31432234, 2019). "Consistent with a relevant pathological role for GRK2-medited changes in Pin1 acetylation status, GRK2 expression and Pin1 levels and de-acetylation status correlate in both cell models and in samples from breast cancer patients." (PMID 31432234, 2019). "On the contrary, silencing GRK2 expression has opposite effects in both luminal and basal breast cancer cells." (PMID 31432234, 2019). "Analysis of the human breast cancer TCGA database shows that GRK2 mRNA is expressed at statistically significantly higher levels in tumor cells compared to normal breast tissue, which is in line with increased protein levels detected in breast cancer patients." (PMID 31432234, 2019). "Consequently, silencing GRK2 expression sensitizes breast cancer cells to the apoptotic effects of genotoxic drugs." (PMID 39198399, 2024). "Indeed, increased expression of GRK2 potentiate several malignant features of breast cancer cells, and its levels positively correlate with tumor growth and increased metastasis occurrence." (PMID 36233192, 2022). "Altogether, these results suggested that the increased expression of GRK2 noted in the breast cancer cell lines and in patients, would also contribute to tumor progression by fostering the cellular mechanisms that induce and stabilize the HIF-1α protein in normoxia." (PMID 32413989, 2020). "In breast cancer cells, GRK2 phosphorylates HDAC6, leading to tumor growth." (PMID 33256128, 2020). "Interestingly, enhanced GRK2 and HuR expression correlate in luminal breast cancer patients." (PMID 32413989, 2020). "Therefore, we addressed whether chronic β2-adrenergic receptor stimulation promoted HuR regulation by GRK2 in MCF7 breast cancer cells." (PMID 32413989, 2020).
breast cancer (continued). "Notably, GRK2 protein levels are increased in a variety of breast cancer cell lines, in spontaneous mammary tumors developing in MMTV-HER2 transgenic mice, and in a significant proportion of two independent groups of invasive ductal carcinoma patients, in which luminal subtypes predominate." (PMID 31432234, 2019). "For example, downregulation of GRK2, GRK3, GRK5, and GRK6 promoted tumorigenesis and metastasis in Kaposi sarcoma, basal-like breast cancer, colon cancer, and medulloblastoma." (PMID 35769816, 2022). "Of note, the secretion of VEGF-C, a potent inducer of lymphatic vessels through which breast cancer cells often disseminate was strongly increased in the MCF7 cells overexpressing GRK2 as compared to the parental cells, and conversely secretion was reduced upon GRK2 downregulation." (PMID 32413989, 2020). "Therefore, it is tempting to suggest that GRK2 might impact VEGF-C expression via pathways downstream of HuR phosphorylation to foster lymphangiogenesis and metastases of luminal breast cancer cells." (PMID 32413989, 2020). "In breast cancer, the prognostic significance of GRK6 or its role in modulating cancer metastasis remains largely unknown even though GRK2 and GRK4, not GRK3, upregulation have been found to promote tumorigenesis, migration/invasion and metastasis in breast cancer cells." (PMID 39741338, 2024).
ischemia (13 papers, 2013 to 2025). A hypoperfusion of the BLOOD through an organ or tissue caused by a PATHOLOGIC CONSTRICTION or obstruction of its BLOOD VESSELS, or an absence of BLOOD CIRCULATION. "It has previously been demonstrated that the phosphorylation of GRK2 at Ser670 is necessary for GRK2 translocation into mitochondria following ischemia/reperfusion (IR) damage in vitro, and this localization induces apoptosis." (PMID 40076919, 2025). "The ability of PH1 to regulate GRK2 localization represents a promising therapeutic strategy for conditions where hypoxia and oxidative stress play critical roles, such as ischemia, neurodegeneration, or CVDs." (PMID 40659632, 2025). "In a rat hind limb ischemia model, ischemia induces the upregulation of GRK2 protein levels in skeletal muscle." (PMID 34335610, 2021). "The data indicate that GRK2 phosphorylation at Ser-670 in ischemia or at Ser-685 in early reperfusion, which respectively aggravate proteasome- and calpain-mediated GRK2 degradation." (PMID 35111168, 2021). "These collective observations are in agreement with IR studies demonstrating reduced β-AR density and elevated GRK2 levels post-ischemia." (PMID 31387264, 2019). "In the present study, to determine the effect of HF on GRK-2 expression, cardiac biopsies were collected from the LV of patients who suffered from HF with ischemia at the Houston Methodist DeBakey Heart & Vascular Center, Houston, Texas." (PMID 30024944, 2018). "The functional role of GRK2 in cardiac fibroblasts was recently identified and GRK2 modulates contractility and remodeling following ischemia/reperfusion injury." (PMID 30538631, 2018). "Moreover, βARKct gene therapy in a hindlimb ischemia (HI) model induced GRK2 inhibition and promoted subsequent angiogenesis by suppressing ischemia-induced β2AR downregulation, but the detailed mechanism remains to be explored." (PMID 34335610, 2021). "However, whether spironolactone exerts its protective, anti-ischemia effects, at least in part, through the inhibition of GRK2, and thus restoring cardiac insulin and/or β1AR sensitivity, is currently unknown." (PMID 31447681, 2019).
Alzheimer disease (11 papers, 2009 to 2026). A progressive, neurodegenerative disease characterized by loss of function and death of nerve cells in several areas of the brain leading to loss of cognitive function such as memory and language. "Increased GRK2 levels are also associated with the degree of cognitive impairment that is typically observed in Alzheimer's disease." (PMID 39438268, 2024). "As another example, both GRK2 mRNA and protein expression are higher in lymphocytes from patients with Alzheimer’s disease (AD) compared to lymphocytes from healthy controls." (PMID 33546162, 2021). "The author has shown a clear connection between G-protein receptor kinase 2 (GRK2) and AD, which was the basis for the concept of the heart-brain connection in vascular AD, vascular dementia (VaD) and other forms of Alzheimer disease." (PMID 32235574, 2020). "The first evidence of GRK2 localization at mitochondria comes from the study of Obrenovich’s group in a rat model of Alzheimer disease." (PMID 30809146, 2019). "In the early pathogenesis of Alzheimer Disease and in ischemia-reperfusion brain injury models, GRK2 accumulates in damaged mitochondria, suggesting a role for the kinase in this organelle." (PMID 30809146, 2019). "GRK2 levels in the brain is increased during early stages of damage in Alzheimer's disease patients and consequently, GRK2 was predicted to be a marker for early hypoperfusion-induced brain damage, which is associated with mitochondrial damage found in Alzheimer's disease patients." (PMID 35386975, 2021). "Searching for a connection between GRK2 and the neurodegenerative Alzheimer disease (AD), we find increased aggregated serine-670-phosphorylated GRK2 (phospho-S670-GRK2) in brains of AD mice and patients with dementia likely due to AD." (PMID 41895286, 2026). "We have shown a clear connection for VaD and AD centering on G-protein-coupled receptor kinase 2 (GRK2) and AD, which was the basis for the concept of the heart–brain connection in vascular AD, vascular dementia, and other forms of Alzheimer’s disease." (PMID 36675988, 2022).
diabetes (11 papers, 2017 to 2026). "Indeed, elevated GRK2 levels in lymphocytes is associated with diabetes, and kinase levels increase in the myocardial tissue and the PBMCs at the early stage of diabetes in db/db mice." (PMID 33467677, 2021). "Interaction between GRK2 and Akt has been shown to suppress Akt kinase activity, contributing to endothelial dysfunction in diabetes and metabolic disorders." (PMID 41602450, 2026). "GRK2 is a key contributor to vascular endothelial dysfunction in diabetes by inhibiting the AKT/eNOS pathway in endothelial cells." (PMID 33467677, 2021). "Findings from animal models of diabetes show that GRK2 silencing in the liver significantly improves glucose homeostasis, but also ameliorates diabetes-dependent endothelial dysfunction." (PMID 33467677, 2021). "Second, studies show that GRK2 expression is not only related to energy metabolism disorder of diabetes but also plays a key role in diastolic function and systolic function." (PMID 31680450, 2020). "The GRK2 mRNA level in PBMCs of diabetes patients with LVDD was significantly increased than that of the diabetic controls without LVDD with age and HbA1C adjusted." (PMID 31680450, 2020). "GRK2 inhibition represents a promising therapeutic target for diabetes and its cardiovascular complications." (PMID 30934608, 2019). "This is the first observation of the beneficial use of GRK2 inhibitors in cardiac alterations in diabetes." (PMID 30934608, 2019). "Our findings provide evidence that GRK2 can be an innovative therapeutic target for diabetes, with positive effects on diabetic cardiopathy." (PMID 30934608, 2019). "Our paper provides the evidence that GRK2 inhibition can be safely achieved through means of engineered peptides targeting the HJ loop of the kinase, with beneficial effects in diabetes." (PMID 30934608, 2019). "Our data are in accordance with this literature, and in particular, the effect of KRX-C7 to reduce mRNA of SERCA2a confirms the maladaptive upregulation of SERCA2a in diabetes, and the effectiveness of GRK2 inhibition to correct such a feature." (PMID 30934608, 2019). "In animal models of diabetes, inhibition of GRK2 and GRK3 through synthetic peptides rescues glucose tolerance and improves insulin sensitivity." (PMID 30538631, 2018). "In animal models of diabetes, inhibition of GRK2 and GRK3 through these synthetic peptides rescues glucose tolerance and enhances insulin sensitivity." (PMID 30538631, 2018). "Besides its ability to regulate glucose homeostasis, GRK2 also regulates other molecular mechanisms that contribute to the development of diabetes and its complications, such as endothelial and cardiac dysfunction." (PMID 33467677, 2021). "Several studies support the role of GRK2 in the development and progression of diabetes." (PMID 33467677, 2021). "The role of GRK2 as crucial node between HF and diabetes has been confirmed in humans as well." (PMID 30147654, 2018). "In addition, GRK2 may be an important contributor to renal vascular endothelial dysfunction in diabetes." (PMID 39438268, 2024). "In fact, lymphocyte GRK2 protein levels are significantly increased in patients with diabetes mellitus and HF compared to failing non-diabetics patients, suggesting further compromised cardiac β-AR signaling/function." (PMID 30147654, 2018).
myocardial ischemia (10 papers, 2013 to 2024). A disorder of cardiac function caused by insufficient blood flow to the muscle tissue of the heart. "Knockout of GRK2 in fibroblasts conferred a protective advantage after myocardial ischemia/reperfusion injury." (PMID 33500351, 2021). "Previous studies showed that LV GRK2 levels were increased in patients with idiopathic cardiomyopathy, volume overload, cardiac ischemia, and LV hypertrophy." (PMID 30024944, 2018). "Since GRK2 appears to also act as a pro-death kinase in myocytes, we investigated the effect of cardiomyocyte-specific GRK2 ablation on the acute response to cardiac ischemia/reperfusion (I/R) injury." (PMID 23805205, 2013). "These GRK2 KO mice and appropriate control mice were subjected to a sham procedure or 30 min of myocardial ischemia via coronary artery ligation followed by 24 hrs reperfusion." (PMID 23805205, 2013). "Moreover, GRK2 high expression is detected in patients with end-stage dilated HF and in several conditions related to HF development, including myocardial ischemia and hypertension." (PMID 30538631, 2018).
endothelial dysfunction (9 papers, 2017 to 2026). In vascular diseases, endothelial dysfunction is a systemic pathological state of the endothelium (the inner lining of blood vessels) and can be broadly defined as an imbalance between vasodilating and vasoconstricting substances produced by (or acting on) the endothelium. "Thus, the increased expression of GRK2 observed in vessels from different mouse models of vascular or metabolic diseases can be an underlying factor that decreases NO bioavailability and contributes to endothelial dysfunction." (PMID 30837878, 2019). "This study aims to investigate the protective role of mitochondrial GRK2 in hypoxia-induced endothelial dysfunction using a peptide based on the sequence of βARK-ct." (PMID 40659632, 2025). "Specifically, the present study provides evidence that acute normalization of glucose homeostasis increases Akt/eNOS signaling and NO bioavailability after GRK2-induced endothelial dysfunction." (PMID 28814745, 2017). "In conclusion, our study using ob/ob mice has shown that inhibition of hepatic GRK2 expression is sufficient to improve glucose homeostasis and insulin sensitivity, which eventually improves endothelial dysfunction in T2DM." (PMID 28814745, 2017). "We have previously shown that chemical inhibition of G-protein-coupled receptor kinase 2 (GRK2) slightly enhances insulin sensitivity and reduces endothelial dysfunction in type 2 diabetic mice." (PMID 28814745, 2017). "Liver-targeting GRK2 siRNA delivery represents a novel therapeutic tool to restore glucose homeostasis and reduce endothelial dysfunction." (PMID 28814745, 2017). "The enhanced vascular reactivity in isolated swine vessels suggests that GRK2 may have therapeutic implications, improving vascular function in diseases characterized by endothelial dysfunction." (PMID 40659632, 2025). "This study highlights GRK2 is a central mediator in OSS‐induced endothelial dysfunction." (PMID 40492401, 2025). "For instance, chronic AngII treatment of C57Bl6 mice upregulates GRK2 in vessels, leads to inhibition of the Akt/eNOS pathway, and thus reduces NO production both basally and after AngII-infusion that finally results in endothelial dysfunction." (PMID 30837878, 2019). "It remains to be established whether inhibition of GRK2 in the liver reduces endothelial dysfunction by restoration of glucose homeostasis and insulin sensitivity or vice versa." (PMID 28814745, 2017). "We sought to determine whether hepatic GRK2 siRNA transfection would improve endothelial dysfunction via GRK2 regulation of glucose metabolism and insulin sensitivity." (PMID 28814745, 2017). "Coherently, the increased expression of GRK2 observed in vessels from different mouse models of vascular or metabolic diseases correlates with a decrease in NO bioavailability that may contribute to endothelial dysfunction." (PMID 33020373, 2020). "More importantly, GRK2 inhibition or partial GRK2 deletion improved the endothelial dysfunction observed in obese/diabetic or hypertensive animal models by restoring the impaired Akt/eNOS pathway and NO availability in a process in which glucose homeostasis may be implicated." (PMID 30837878, 2019). "Taken together, these findings indicate that FF improves lipid metabolism and HFD-induced endothelial dysfunction by enhancing the LKB1/AMPK/Akt signaling pathway and increasing NO production, while simultaneously suppressing hepatic GRK2 overactivation." (PMID 41602450, 2026). "Ex vivo studies suggest the potential role of GRK2 modulation in preserving endothelium-dependent vasodilation induced by Ach during hypoxia, offering a novel treatment approach for endothelial dysfunction that is not based on drug therapies." (PMID 40659632, 2025). "Additionally, knockdown GRK2 significantly reduced the increase in phosphorylated AP‐1 levels induced by OSS, indicating that AP‐1 is a downstream target of GRK2 in mediating OSS‐induced endothelial dysfunction." (PMID 40492401, 2025).
endothelial dysfunction (continued). "Together, these findings suggest that partial or local rather than generalized GRK2 targeting might be considered when increased NO levels and a correction of endothelial dysfunction need to be achieved." (PMID 30837878, 2019). "In this situation, strategies aimed at improving endothelial dysfunction in T2DM in general and restoring GRK2 expression in the liver in particular may provide the basis for the rational design of novel therapies for T2DM and its attendant diabetic vascular complications." (PMID 28814745, 2017).
type 2 diabetes (9 papers, 2011 to 2025). "Furthermore, the phosphorylation of Ser612 is uniquely associated with ET-1 and GRK2 in myocardial ischemic injury; type 2 diabetes." (PMID 26474286, 2015). "In conclusion, our data suggest that MIF are involved in the pathogenesis of LVDD in patients with type 2 diabetes and GRK2 may play a role in mediating MIF's effect." (PMID 21283592, 2011). "Other peptides derived from residues of the substrate-kinase interaction domain in GRK2 and GRK3 have been tested in several animal models of type 2 diabetes." (PMID 30837878, 2019).